AQP4 (aquaporin 4)
Diseases named in the same sentence as AQP4 in open-access papers (continued):
Sharing a sentence is not in itself a finding about the gene and the disease.
neuromyelitis optica spectrum disorder (continued). "Breakthroughs in conditions such as myasthenia gravis and aquaporin-4 IgG-positive neuromyelitis optica spectrum disorder underscore the therapeutic potential of targeting complement pathways to improve patient outcomes." (PMID 41409222, 2025). "We searched PubMed and Google Scholar with a combination of the keywords "neuromyelitis optica" and "organizing pneumonia" and "aquaporin-4" for studies published until December 31, 2024." (PMID 40546576, 2025). "The clinical features of MOGAD partly overlap with multiple sclerosis (MS) and aquaporin-4 antibody (AQP4-Ab) seropositive neuromyelitis optica spectrum disorders (NMOSD-AQP4); however, different immunopathogenetic mechanisms underlie the three diseases." (PMID 40217895, 2025). "Neuromyelitis optica spectrum disorder (NMOSD) is an autoimmune disease characterized by anti-aquaporin 4 (AQP4) antibody-mediated astrocyte damage and subsequent demyelination." (PMID 40686188, 2025). "Its clinical course, immunological features, imaging findings, and response to treatment are different from anti-aquaporin-4 (AQP4) antibody seropositive neuromyelitis optica spectrum disorders (NMOSD) and classical multiple sclerosis (MS)." (PMID 40098969, 2025). "Ravulizumab has emerged as a significant therapeutic option for the treatment of patients with neuromyelitis optica spectrum disorder (NMOSD) who are positive for aquaporin-4 (AQP4) antibodies." (PMID 40400837, 2025). "MOGAD is increasingly recognized as a distinct disease entity different from multiple sclerosis (MS) and aquaporin-4 (AQP4)-positive neuromyelitis optica spectrum disorder (NMOSD) and is more prevalent among children and young adults." (PMID 40904974, 2025). "Magnetic resonance imaging (MRI) is often used to evaluate disease-related brain changes in patients with aquaporin-4-IgG seropositive neuromyelitis optica spectrum disorder (AQP4-IgG+ NMOSD)." (PMID 41362332, 2025). "Neuromyelitis optica spectrum disorder (NMOSD) is a severe autoimmune astrocytopathy mediated by aquaporin-4-immunoglobulin G (AQP4-IgG) antibodies, leading to complement-mediated neural injury." (PMID 40400837, 2025). "MOGAD is a distinct autoimmune disorder separate from multiple sclerosis (MS) and aquaporin-4 antibody-positive neuromyelitis optica spectrum disorder (AQP4 Ab+ NMOSD)." (PMID 41393590, 2025). "Recent investigations have further elucidated that neutrophils synergize with anti-AQP-4 antibodies to promote astrocyte destabilization and glutamate transporter dysfunction in neuromyelitis optica spectrum disorder (NMOSD)." (PMID 40854886, 2025). "MOG antibody-associated disease (MOGAD) is an autoimmune inflammatory disorder of the central nervous system (CNS), distinct from multiple sclerosis (MS) and aquaporin-4 antibody-positive neuromyelitis optica spectrum disorder (AQP4 Ab+ NMOSD)." (PMID 41393590, 2025). "Neuromyelitis optica spectrum disorders (NMOSDs), also known as Devic’s disease, primarily affect the optic nerves and spinal cord and are characterized by autoantibodies against aquaporin-4 water channels on astrocytes." (PMID 40429767, 2025). "Previous studies have indicated that progression independent of relapse activity (PIRA) is uncommon in patients with aquaporin- 4 antibody-positive (AQP4-IgG) neuromyelitis optica spectrum disorder (NMOSD)." (PMID 40227344, 2025). "Aquaporin-4 neuromyelitis optica spectrum disorder (NMOSD) is an autoimmune disorder of the central nervous system (CNS) that primarily targets astrocytes, leading to inflammation, demyelination." (PMID 40495001, 2025). "As demonstrated in aquaporin-4 (AQP4)-IgG positive neuromyelitis optica spectrum disorder (AQP4 + NMOSD), knowledge of the pathophysiology of autoimmune neurological conditions is the most important step for the development of tailored treatments." (PMID 39891565, 2025).
neuromyelitis optica spectrum disorder (continued). "B-cell-targeting monoclonal antibodies have demonstrated safety and efficacy in multiple sclerosis or anti-aquaporin-4 IgG positive neuromyelitis optica spectrum disorder." (PMID 39276207, 2024). "Data on peripheral blood mononuclear cells (PBMCs) characteristics of aquaporin‐4 (AQP4)‐IgG seropositive neuromyelitis optica spectrum disorder (NMOSD) and myelin oligodendrocyte glycoprotein antibody‐associated disease (MOGAD) are lacking." (PMID 38334017, 2024). "Neuromyelitis Optica spectrum disorder (NMOSD) is an autoimmune disease characterized by anti-aquaporin-4 (AQP4) auto-antibodies." (PMID 39238786, 2024). "Myelin oligodendrocyte glycoprotein antibody disease (MOG-AD) poses a diagnostic challenge, often masquerading as other neurological disorders such as multiple sclerosis and aquaporin-4-positive neuromyelitis optica spectrum disorder." (PMID 38975430, 2024). "MS, ON, neuromyelitis optica (NMO), optical coherence tomography (OCT), neuritis, NMOSD, MOG, magnetic resonance imaging (MRI), AQP4 and diagnostic criteria were high-frequency keywords." (PMID 38342798, 2024). "Patient 1 (A.II.3) presented at the age of 8 years with anti–aquaporin-4 antibody–positive neuromyelitis optica." (PMID 38175705, 2024). "Eculizumab, a humanized monoclonal antibody approved for the treatment of aquaporin-4-positive neuromyelitis optica spectrum disorders, has undergone investigation for its safety and efficacy in MS." (PMID 38375484, 2024). "Neuromyelitis optica spectrum disorder also known as Devic's disease is an autoimmune condition where the body produces antibodies against Aquaporin-4 in the astrocytes." (PMID 40655048, 2024). "For example, CT103A in refractory AQP4-IgG neuromyelitis optica have been tested on 12 patients and reports a safety profile similar to other approved CAR-T with a drug-free remission for eleven patients in a short follow-up." (PMID 38390873, 2024). "More recently, in aquaporin-4 (AQP4) positive neuromyelitis optica spectrum disorder (NMOSD), the anti-CD19 antibody inebilizumab as well as the IL6-receptor blocking agent satralizumab, which interferes with B-cell activation, have demonstrated efficacy." (PMID 39276207, 2024). "Aquaporin-4-antibody-seropositive (AQP4-IgG+) Neuromyelitis Optica Spectrum Disorder (NMOSD) and Myelin Oligodendrocyte Glycoprotein Antibody-Associated Disorder (MOGAD) are relapsing neuroinflammatory diseases, frequently leading to chronic pain." (PMID 38343712, 2024). "In neuromyelitis optica spectrum disorders, an unusual nervous autoimmune disorder often featured with circulating IgG autoantibody against AQP4, the impairment in astrocyte water homeostasis has been observed." (PMID 39508543, 2024). "Antibodies against AQP1 (anti-AQP1) and AQP4 (anti-AQP4) have consistently been identified in the sera of patients afflicted with neuromyelitis optica (NMO)." (PMID 39441465, 2024). "An ongoing phase I clinical trial has indicated the safety and benefits of anti-BCMA CAR T cells in 12 patients with AQP4-IgG seropositive neuromyelitis optica spectrum disorder." (PMID 39276207, 2024). "For example, neuromyelitis optica spectrum disorder (NMOSD) was once considered a subtype of MS but is now recognized as a separate disease since NMOSD patients have anti-aquaporin 4 (AQP4) antibodies." (PMID 39237437, 2024). "AQP4-Ab positivity is a strong marker for neuromyelitis optica spectrum disorder, a severe autoimmune inflammatory disorder of the CNS, marked by intense optic neuritis and myelitis." (PMID 39081310, 2024). "Despite the role of AQPs in SCI and SCI related conditions, AQP4 has gained increased interest due to its role in neuromyelitis optica spectrum disorder." (PMID 38818518, 2024). "This case series describes adults with aquaporin 4 immunoglobulin G–seropositive (AQP4-IgG+) neuromyelitis optica spectrum disorder (NMOSD) who switched treatment from eculizumab to satralizumab." (PMID 39867894, 2024).
neuromyelitis optica spectrum disorder (continued). "Diagnosis of neuromyelitis optica involves MRI of the brain and spinal, cord and by testing blood serum for AQP4-antibodies." (PMID 39430225, 2024). "Distinct from multiple sclerosis (MS) and aquaporin-4-seropositive neuromyelitis optica spectrum disorder (AQP4-NMOSD), MOGAD can follow a monophasic or relapsing disease course and is characterised by the presence of antibodies against MOG." (PMID 38758280, 2024). "Neuromyelitis Optica Spectrum Disorders (NMOSD) comprise a group of autoimmune-mediated, inflammatory, demyelinating central nervous system diseases caused by aquaporin-4 (AQP4) IgG autoantibodies." (PMID 39709432, 2024). "The immune system is tolerized against the neuromyelitis optica autoantigen AQP4 by thymic B cells, which present their endogenous AQP4 to AQP4-reactive thymocytes." (PMID 38383779, 2024). "MOGAD is now recognized as a distinct disease entity with an immunopathogenesis that differs from both multiple sclerosis (MS) and AQP4-IgG-positive neuromyelitis optica spectrum disorder (NMOSD)." (PMID 39493140, 2024). "It is important to note that the disease characteristics, immunopathology, and treatment response of MOGAD patients differ from those of anti-aquaporin 4 antibody-positive neuromyelitis optica spectrum disorders (NMOSDs) and multiple sclerosis (MS)." (PMID 37686172, 2023). "Aquaporin-4 (AQP4) antibody-seropositive optic neuritis (AQP4-ON) is a phenotype of neuromyelitis optica spectrum disorder (NMOSD)." (PMID 37840923, 2023). "Neuromyelitis Optica spectrum disorder (NMOSD) is a relapsing autoimmune disease of the central nervous system (CNS) where aquaporin-4 water channels are the antigenic target of the disease." (PMID 38982999, 2023). "We measured NMO-IgG (anti-AQP4 autoantibody) in five patients suspected of neuromyelitis optica spectrum disorders and found two patients be positive for this autoantibody." (PMID 36401063, 2023). "Several reported cases of autoimmune conditions such as anti-NMDAR encephalitis and neuromyelitis optica (AQP4) have been considered to be potentially secondary to Treponema pallidum infection." (PMID 37346161, 2023). "Two patients had multiple sclerosis, both with an elevated IgG index and OCB type 3, another patient had neuromyelitis optica spectrum disorder with positive anti-aquaporin 4 antibodies and OCB type 3, but normal IgG index." (PMID 37000850, 2023). "There have been many advancements in the field of neuromyelitis optica and neuromyelitis optica spectrum disorder since the discovery of aquaporin-4 (AQP4) and myelin oligodendrocyte glycoprotein antibodies." (PMID 37581199, 2023). "Inebilizumab, a humanized, glycoengineered, IgG1 monoclonal antibody that depletes CD19+ B‐cells, is approved to treat aquaporin 4 (AQP4) IgG‐seropositive neuromyelitis optica spectrum disorder (NMOSD)." (PMID 37804003, 2023). "Eculizumab, a humanized monoclonal antibody targeting the C5 complement protein, has been approved for the treatment of neuromyelitis optica spectrum disorders (NMOSD) in adult patients who are anti-aquaporin-4 (AQP4) antibody positive (Ab+)." (PMID 38318238, 2023). "Additional investigations include serum studies to identify antibodies specific to MS mimics, such as anti-aquaporin-4 antibodies for neuromyelitis optica spectrum disorder (NMOSD) and an antinuclear antibody (ANA) panel for rheumatologic conditions." (PMID 37841344, 2023). "Neuromyelitis optica spectrum disorders (NMOSD) are severe inflammatory disorders of the central nervous system targeting aquaporin‐4 (AQP4)." (PMID 37296187, 2023). "The autoimmune antibodies from the patients of neuromyelitis optica can target AQP4 on the surface of ECs to trigger the functional impairment and inflammatory response in ependyma." (PMID 37238624, 2023). "Most patients with neuromyelitis optica spectrum disorders (NMOSD) test positive for aquaporin-4 antibody (AQP4-IgG) or myelin oligodendrocyte glycoprotein antibodies (MOG-IgG)." (PMID 37740717, 2023).
neuromyelitis optica spectrum disorder (continued). "Neuromyelitis optica was diagnosed with positive AQP4-IgG and longitudinally extensive transverse myelitis." (PMID 37303442, 2023). "Neuromyelitis optica spectrum disorders (NMOSDs) are central nervous system inflammatory conditions, now recognized to involve the brain, often identified by aquaporin-4 (AQP4) antibodies." (PMID 38021935, 2023). "Neuromyelitis optica (NMO) is an autoimmune disorder characterized by aquaporin-4 (AQP4) IgG autoantibodies." (PMID 37575757, 2023). "It was then studied in 2 neurological conditions such as myasthenia gravis and aquaporin-4 (Aqp-4) antibody positive neuromyelitis optica spectrum disorder (NMOSD), where complement involvement is seen but less well-delineated." (PMID 37869140, 2023). "In neuromyelitis optica, it is well established that autoantibodies directed against Aquaporin-4 are drivers of disease, and it has been shown recently that these autoantibodies can drive ependymal cell dysregulation." (PMID 37771929, 2023). "Spinal MRI findings range from T2 hyperintense lesions, especially in the cervical region, to longitudinally extensive lesions similar to those seen in patients with aquaporin-4–positive Neuromyelitis Optica (NMO)." (PMID 38157875, 2023). "Yet, the distinction of MOGAD-defining characteristics from characteristics of its important differential diagnoses such as multiple sclerosis (MS) and aquaporin-4 antibody seropositive neuromyelitis optica spectrum disorder (NMOSD) is still obstructed." (PMID 38333186, 2023). "Although more commonly an idiopathic autoimmune phenomenon, a paraneoplastic myelitis can occur in the setting of neuromyelitis optica spectrum disorder (NMOSD) mediated by aquaporin-4 (AQP4) antibodies." (PMID 36781586, 2023). "Findings of longitudinal extensive transverse myelitis with positive aquaporin-4 antibodies confirmed the diagnosis of neuromyelitis optica." (PMID 37456991, 2023). "Given the high specificity of AQP4 antibodies, the patient was diagnosed with neuromyelitis optica (NMO) encephalitis." (PMID 38046734, 2023). "Autoreactive B cells from individuals with neuromyelitis optica spectrum disorder (NMOSD) can produce AQP4 IgG following IL-6 stimulation in conjunction with CD4+ T cells." (PMID 39128069, 2023). "Interleukin-6 not only induces acute phase reactions but also induces autoantibody production, such as anti-aquaporin 4 autoantibody production in neuromyelitis optica." (PMID 37025699, 2023). "Cultured porcine astrocytes also express aquaporin 4 (AQP4), enhance neuronal survival, and demonstrate a dose-dependent loss of GFAP when exposed to sera from patients with Neuromyelitis optica, which is a disease characterized by astrocyte loss." (PMID 37760829, 2023). "Patients with aquaporin-4 antibody-positive neuromyelitis optica spectrum disorder (AQP4 + NMOSD) were reported to demonstrate worse outcomes compared with patients with anti-myelin oligodendrocyte glycoprotein-associated disorders (MOGAD)." (PMID 36864239, 2023). "Antibodies against AQP4 (AQP4-Abs) were first identified in 2005 in patients with neuroinflammation who are now best defined as having neuromyelitis optica spectrum disorders (NMOSDs)." (PMID 37208665, 2023). "Compared with other patients with aquaporin 4 positive neuromyelitis optica spectrum disorder, MOGAD patients are often accompanied by optic disc edema." (PMID 38065923, 2023). "MOGAD patients always present with severe visual impairment, and a better vision recovery prognosis than aquaporin 4 positive neuromyelitis optica spectrum disorder." (PMID 38065923, 2023). "The tentative diagnosis was encephalitis; however, this patient was found to have neuromyelitis optica as an anti-aquaporin 4 antibody was detected." (PMID 35322140, 2022).
neuromyelitis optica spectrum disorder (continued). "The diseases included rheumatoid arthritis, systemic lupus, Sjogren's syndrome, localized scleroderma, psoriasis, celiac disease, Graves's disease, neuromyelitis optica with positive antibodies against aquaporin 4, and myasthenia gravis." (PMID 35923829, 2022). "An example of the importance of the two-dimensional supramolecular organization of antigen in the membrane for the activation of complement has been described by researchers working on the aquaporin-4 (AQP4) autoantibody response in neuromyelitis optica." (PMID 36074148, 2022). "In contrast, a high signal intensity of intramedullary spinal cord on a T2-weighted image from C1 to conus medullaris and positive anti-aquaporin-4 antibody confirmed neuromyelitis optica spectrum disorder (NMOSD)." (PMID 35891192, 2022). "This has also diagnostic and therapeutic consequences: the detection of antibodies to AQP-4 is a highly suggestive marker for the autoimmune disorder neuromyelitis optica, while AQP-4 is recently considered a valuable target in treating cerebral edema." (PMID 36009030, 2022). "AQP4 has also been shown to play an important role in the pathophysiological processes of encephaledema, brain tumors, epilepsy, and neuromyelitis optica." (PMID 35991296, 2022). "Some patients with typical clinical manifestations for neuromyelitis optica are consistently seronegative for AQP4-IgG." (PMID 36016923, 2022). "Inebilizumab is an anti-CD19 antibody approved for the treatment of neuromyelitis optica spectrum disorder (NMOSD) in adults with aquaporin-4 autoantibodies." (PMID 36370634, 2022). "By studying paired blood and deep cervical lymph node samples from patients with neuromyelitis optica spectrum disorders, our data provide evidence for a germinal center–based generation of aquaporin-4 antibodies." (PMID 35666871, 2022). "Recognizing the predictors of disease relapses in patients with anti-aquaporin-4 antibody (AQP4-ab)-positive neuromyelitis optica spectrum disorder (NMOSD) is essential for individualized treatment strategy." (PMID 35432315, 2022). "Concentrations of 26 cytokines and chemokines were determined in CSF of 28 treatment-naïve MS patients and 12 disease-control patients with aquaporin-4 antibody-seropositive neuromyelitis optica spectrum disorder (NMOSD)." (PMID 36203996, 2022). "Serum antibodies to myelin-oligodendrocyte glycoprotein (MOG) are biomarkers of MOG-IgG-associated disorder (MOGAD), a demyelinating disease distinct from both multiple sclerosis (MS) and aquaporin-4-IgG neuromyelitis optica spectrum disorder (NMOSD)." (PMID 36002821, 2022). "We compared the patterns of relapse in later stages of MOGAD with those of anti-aquaporin-4 antibody (AQP4-Ab)-positive neuromyelitis optica spectrum disorder (NMOSD)." (PMID 34820735, 2022). "Aquaporin-4-antibody neuromyelitis optica spectrum disorders were diagnosed in three (2.4%, 0.26/million children/year), and relapsing myelin oligodendrocyte glycoprotein antibody-associated disease in five (4%, 0.43/million children/year)." (PMID 34693523, 2022). "In neuromyelitis optica, autoantibodies are produced against the astrocyte water channel protein aquaporin 4 (AQP4)." (PMID 36045671, 2022). "Anti-aquaporin 4 (AQP4) antibody (AQP4-Ab) is involved in the pathogenesis of neuromyelitis optica spectrum disorder (NMOSD)." (PMID 34991631, 2022). "Summary of sex bias in relapsing multiple sclerosis (MS) and AQP4-antibody seropositive neuromyelitis optica spectrum disorders (NMOSD)." (PMID 36016923, 2022). "Aquaporin-4 antibody (AQP4-Ab) Neuromyelitis Optica Spectrum Disorder (NMOSD) is a rare neuroinflammatory syndrome presenting predominantly with optic neuritis and transverse myelitis." (PMID 35332817, 2022). "Neuromyelitis optica spectrum disorders (NMOSD) is an inflammatory central nervous system demyelinating syndrome, which is usually associated with serum anti-aquaporin-4 (AQP4) antibody (AQP4+ NMOSD)." (PMID 36517738, 2022).